PSMD14 (proteasome 26S subunit, non-ATPase 14)
Diseases named in the same sentence as PSMD14 in open-access papers (continued):
Sharing a sentence is not in itself a finding about the gene and the disease.
pancreatic cancer (4 papers, 2023 to 2025). "In conclusion, this study revealed the important roles of PSMD11 and PSMD14 in pancreatic cancer and provided insights into their underlying mechanisms." (PMID 40182048, 2025). "Since the expression of PSMD11 and PSMD14 in pancreatic cancer tissues was significantly higher than that in normal tissues, we hypothesized that PSMD11 and PSMD14 might have diagnostic and prognostic value in pancreatic cancer." (PMID 40182048, 2025). "Our analysis revealed significant upregulation of PSMD11 and PSMD14 in several tumors, including pancreatic cancer." (PMID 40182048, 2025). "Subsequently, we measured the levels of intracellular triglycerides (TG), free fatty acids, and cholesterol in pancreatic cancer cells to assess the effect of PSMD14 on lipid metabolism in pancreatic cancer cells." (PMID 41051446, 2025). "Second, the role of PSMD11 and PSMD14 in pancreatic cancer metastasis and prognosis, and their potential value in individualized therapy, merit further exploration." (PMID 40182048, 2025). "In conclusion, the mRNA expression levels of PSMD11 and PSMD14 were significantly higher in pancreatic cancer tissues compared with normal pancreatic tissues." (PMID 40182048, 2025). "In this study, we verified that the expression of the proteasome protein PSMD11 and the deubiquitinating enzyme PSMD14 in pancreatic cancer was increased in PDAC tissues." (PMID 40182048, 2025). "In our study, we found that PSMD14 upregulation promotes de novo fatty acid synthesis and cell proliferation in pancreatic cancer cells, leading to poor patient survival outcomes." (PMID 41051446, 2025). "To further validate these findings, we performed global lipidomic profiling via mass spectrometry to systematically compare lipid composition between PSMD14‐overexpressing pancreatic cancer (PC) cells and empty vector controls." (PMID 41051446, 2025). "We found that PSMD11 and PSMD14 mRNA expression was significantly upregulated in pancreatic cancer tissues compared with normal tissues." (PMID 40182048, 2025). "Knockdown of PSMD11 and PSMD14 significantly inhibited the proliferation, migration, and invasion ability of pancreatic cancer cells." (PMID 40182048, 2025). "The effects of PSMD11 and PSMD14 on the malignant biological behaviors of pancreatic cancer cells, such as proliferation, migration and invasion, were investigated by in vitro experiments." (PMID 40182048, 2025). "Only H3K18la showed significant elevation following PSMD14 overexpression, leading us to focus on H3K18la's role in pancreatic cancer." (PMID 41051446, 2025). "To characterize the spatial distribution of LDHA and PSMD14, we performed subcellular localization analysis in pancreatic carcinoma cells." (PMID 41051446, 2025). "Our study indicates that inhibiting PSMD14 may improve the therapeutic efficacy in pancreatic cancer, demonstrating potential for clinical application." (PMID 41051446, 2025). "Therapeutic co‐targeting of PSMD14 and glycolytic lactylation significantly suppresses tumor growth in patient‐derived xenograft models, suggesting a promising combinatorial strategy for pancreatic cancer treatment." (PMID 41051446, 2025). "Therefore, both PSMD11 and PSMD14 expression may serve as prognostically relevant markers for pancreatic cancer." (PMID 40182048, 2025). "Notably, we further analyzed the correlations between PSMD11 and PSMD14 expression and the prognosis of patients with pancreatic cancer in the TCGA and GSE28735 databases and divided the tumor samples into high- and low-expression groups according to the optimal segmentation point." (PMID 40182048, 2025). "Subsequently, multiplex immunofluorescence analysis of pancreatic cancer tissues demonstrated co‐upregulation of ACLY and ACC1 proteins in PSMD14‐high tumor regions." (PMID 41051446, 2025).
pancreatic cancer (continued). "And, it was published that PSMD14 was expressed highly in PDAC samples, and its targeting with specific small molecule inhibitors significantly reduced pancreatic tumor formation." (PMID 40066751, 2025). "Notably, although cell‐based experiments indicated that PSMD14 does not affect LDHA transcription, TCGA database analysis revealed a significant positive correlation between their mRNA levels in pancreatic cancer tissues." (PMID 41051446, 2025).
breast tumor (3 papers, 2021 to 2025). "Immunohistochemical (IHC) images revealed dense distributions of PSMD2 and PSMD4, while the other PSMDs, including PSMD1, PSMD2, PSMD3, PSMD7, PSMD12, and PSMD14, were moderately distributed in breast tumor samples." (PMID 34839279, 2021). "For example, PSMD14 promoted positive breast tumor growth by stabilizing estrogen signaling." (PMID 40066751, 2025). "Furthermore, in the xenograft mice model, PSMD14 depletion not only impaired breast tumor growth, but also enhanced the inhibitory effect of tamoxifen in the Y537S-expressing MCF-7 model." (PMID 38017133, 2024). "Furthermore, we investigated the correlation between PSMD14 and classical ERα target genes in breast tumors from the TCGA database." (PMID 38017133, 2024).
gastric cancer (3 papers, 2023 to 2025). A primary or metastatic malignant neoplasm involving the stomach. "We finally verified the mRNA expression of EZH2, G6PD, LGALS3 and PSMD14 by qRT-PCR in clinical gastric cancer tissue samples." (PMID 37853322, 2023).
leukemia (3 papers, 2022 to 2026). A malignant (clonal) hematologic disorder, involving hematopoietic stem cells and characterized by the presence of primitive or atypical myeloid or lymphoid cells in the bone marrow and the blood. "Both genetic knockdown and pharmacological inhibition of PSMD14 recapitulate EB's effects, confirming its essential role in leukemia cell survival and proliferation." (PMID 41647277, 2026). "The newly developed PSMD14 inhibitors, capzimin and thiolutin, also demonstrated robust anti-cancer activity in solid tumors and leukemia cell lines." (PMID 38482057, 2024).
melanoma (3 papers, 2022). A malignant, usually aggressive tumor composed of atypical, neoplastic melanocytes. "Studies on PSMD14 were mainly associated with tumors, for example, targeting PSMD14 inhibited melanoma growth through SMAD3 stabilization." (PMID 35884735, 2022). "As suspected, due to its key role in proteasomal integrity and activity, PSMD14 functional alteration leads to cell viability defects in all species and has recently been studied in melanoma." (PMID 35884430, 2022). "In addition to melanoma cellular proliferation, these findings suggest a role of PSMD14 within the EMT process, as also observed in breast and esophageal cancers." (PMID 35884430, 2022). "At this point, PSMD14 appears to be a promising new therapeutic target in melanoma." (PMID 35884430, 2022).
non-small cell lung carcinoma (3 papers, 2020 to 2023). A group of at least three distinct histological types of lung cancer, including non-small cell squamous cell carcinoma, adenocarcinoma, and large cell carcinoma. "Although accumulating evidence indicates that PSMD14 has emerged as a critical oncogenic factor by promoting tumor growth, the expression and function of PSMD14 in non-small cell lung cancer (NSCLC) remain largely unknown." (PMID 32226511, 2020).
bladder cancer (2 papers, 2022 to 2023). "The association between PSMD14 expression and clinical and pathological data and outcomes of bladder cancer patients was determined." (PMID 36632137, 2023). "Gain and loss of function experiments demonstrated that PSMD14 deficiency inhibited bladder cancer cell proliferation." (PMID 36632137, 2023). "The aim of this study was to investigate the role of deubiquitinase (DUB) 26S proteasome non-ATPase regulatory subunit 14 (PSMD14) in patients with bladder cancer." (PMID 36632137, 2023). "We determined that PSMD14 is highly expressed in bladder cancer tissues, and that PSMD14 expression correlated with poor disease-free survival." (PMID 36632137, 2023). "Overexpression and knockdown cells were constructed to evaluate the effects of PSMD14 on proliferation of bladder cancer cells." (PMID 36632137, 2023). "The expression of PSMD14 in bladder cancer tissues was tested by immunochemistry." (PMID 36632137, 2023). "Additionally, depletion of PSMD14 suppressed bladder cancer cell growth via down-regulation of GPX4, and the promotion of PSMD14-induced cell growth was observably reversed by the GPX4 inhibitor RSL3." (PMID 36632137, 2023). "Depletion of PSMD14 could inhibit the proliferation of bladder cancer cells through the downregulation of GPX4." (PMID 36632137, 2023). "Therefore, PSMD14 may be an effective target for the treatment of bladder cancer." (PMID 36632137, 2023). "We obtained the results of immunohistochemical staining of PSMD14, PRPF19, PSMB5, and TPR in normal tissues and bladder cancer tissues and demonstrated that these four genes were highly expressed in tumor tissues and lowly expressed in normal tissues." (PMID 35898492, 2022). "Our results showed that PSMD14 was significantly overexpressed in bladder cancer tissues compared to adjacent non-tumor tissues (76.24% vs 23.76%, P = 0.02)." (PMID 36632137, 2023).
Epstein-Barr virus infection (2 papers, 2017 to 2023). An infection that is caused by Epstein-Barr virus. "Apart from being present in proteasome subunits, PSMD14 and PSMA3 were associated with Epstein-Barr virus infection." (PMID 28626423, 2017). "Specifically, SIRT6 was enriched in thermogenesis, while PSMD14 and PSMC6 were enriched in Epstein-Barr virus infection, and NCBP2 and PYM1 were enriched in nucleocytoplasmic transport." (PMID 37958518, 2023).
Insulin resistance (2 papers, 2025). Increased resistance towards insulin, that is, diminished effectiveness of insulin in reducing blood glucose levels. "In hepatocytes, the inhibition of PSMD14 (RPN11) deubiquitinase protects against hepatic steatosis and insulin resistance induced by a high-fat diet." (PMID 40867854, 2025).
autoimmune disease (1 paper, 2020). A disorder resulting from loss of function or tissue destruction of an organ or multiple organs, arising from humoral or cellular immune responses of the individual to their own tissue constituents. "In addition, the other genes listed include PSMD14 and TNFRSF12A, which are related to key targets in the TNF pathway of autoimmune diseases." (PMID 33299893, 2020).
dependence (1 paper, 2025). "Additionally, KEGG pathway analysis has demonstrated that PSMD14 is significantly enriched in signaling pathways associated with the cell cycle and nicotine dependence, indicating its integral role in a multitude of biological processes." (PMID 40475775, 2025).
dysplasia (1 paper, 2021). A usually neoplastic transformation of the cell, associated with altered architectural tissue patterns. "The results of IHC confirmed that the protein expression of PSMD14 was much higher in low-grade dysplasia (Week 24) and high-grade dysplasia/carcinoma (Week 28) than that in normal tissue (Week 16), indicating that PSMD14 may be implicated in HNSCC tumorigenesis." (PMID 33456565, 2021).
Fanconi anemia (1 paper, 2023). Fanconi anemia (FA) is a hereditary DNA repair disorder characterized by progressive pancytopenia with bone marrow failure, variable congenital malformations and predisposition to develop hematological or solid tumors. "The DUB proteins USP1, OTUB1, UCHL5, USP7, and PSMD14 were reported to contribute to double-strand break repair, USP1 to Fanconi anemia pathway, USP1 and USP7 to translesion repair, USP7 and USP47 to base excision repair, and USP7 and USP45 to nucleotide excision repair." (PMID 37892185, 2023).
hepatitis B (1 paper, 2022). "Besides, PSMD14 is implicated in viral replication and pathogenesis in hepatitis B." (PMID 35327634, 2022).
medulloblastoma (1 paper, 2024). A malignant, invasive embryonal neoplasm arising from the cerebellum. "For medulloblastoma, the most significant differences in rank order were observed in CKB, GFAP, and 26S proteasome non-ATPase regulatory subunit 14 (PSMD14)." (PMID 38350915, 2024).
mesothelioma (1 paper, 2025). A usually malignant and aggressive neoplasm of the mesothelium which is often associated with exposure to asbestos. "Our results demonstrate that PSMD14 displays significantly altered expression across a spectrum of malignancies, including lung, liver, pancreas, head, and neck cancers, as well as mesothelioma." (PMID 40475775, 2025). "Notably, elevated PSMD14 expression was markedly strongly linked to unfavorable poor prognoses in patients diagnosed with HNSC, LGG, LIHC, LUAD, mesothelioma (MESO), and PAAD, with the most pronounced association observed in PAAD." (PMID 40475775, 2025).
neuroblastoma (1 paper, 2023). Neuroblastoma (NB) is the most common solid, extracranial childhood tumor. "Cisplatin-chemoresistant neuroblastoma cells have been found to show high expression levels of SHFM1 (i.e., 26S proteasome complex subunit SEM1) and PSMD14 (i.e., 26S proteasome non-ATPase regulatory subunit 14) using transcriptomic profiling." (PMID 37508510, 2023).
nicotine addiction (1 paper, 2025). "Moreover, Kyoto Encyclopedia of Genes and Genomes (KEGG) pathway analysis revealed that PSMD14 is significantly associated with pathways related to the cell cycle and nicotine dependence, underscoring its vital function in modulating cell proliferation and metabolic activities." (PMID 40475775, 2025). "The involvement of PSMD14 in nicotine addiction pathways provokes compelling inquiries regarding its influence on the tumor microenvironment." (PMID 40475775, 2025).
osteoporosis (1 paper, 2025). A condition of reduced bone mass, with decreased cortical thickness and a decrease in the number and size of the trabeculae of cancellous bone (but normal chemical composition), resulting in increased fracture incidence. "Through high‐throughput virtual screening, this work identifies Pantethine as a potent PSMD14 activator that enhances deubiquitinase activity, restores SLC7A11 expression in osteocytes, and mitigates osteoporosis." (PMID 40444470, 2025).
ovarian serous carcinoma (1 paper, 2023). "Among them, up-regulation of PSMD4, PSMD8, and PSMD14 mRNA expression was significantly associated with poor OS in patients with ovarian serous carcinomas." (PMID 37349676, 2023).
ovarian tumor (1 paper, 2021). "In addition, PSMD14 stable knockdown also contributed to significantly lower ovarian tumor weight." (PMID 34382324, 2021).
pancreatic adenocarcinoma (1 paper, 2025). "In our study, GEPIA predicted that a marked upregulation of PSMD14 expression in human pancreatic adenocarcinoma (PAAD) tissues." (PMID 40066751, 2025).
varicocele (1 paper, 2021). A condition characterized by the dilated tortuous veins of the spermatic cord with a marked left-sided predominance. "In particular, the analysis showed 2 (FASN, MPO) and 3 (ACO2, NUP93, and PSMD14) proteins, which were significantly over- and under-expressed, respectively (P <0.03) in varicocele samples and reported to be involved in DNA repair function." (PMID 34975746, 2021).
cancer (56 papers, 2011 to 2026). A tumor composed of atypical neoplastic, often pleomorphic cells that invade other tissues. "While the expression of PSMD14 is associated with particular cancer types, it predominantly correlates with advanced stages of disease, especially in LUAD." (PMID 40475775, 2025). "In several types of cancer, the oncogene PSMD14 has been found to encode deubiquitylation enzymes that function in the ubiquitin pathway." (PMID 39781342, 2025). "Since high expression of PSMD14 is commonly linked to advanced cancer features and studies only occasionally corrected the prognostic value for potential confounders." (PMID 35750900, 2023). "High PSMD14 mRNA and protein expression was associated with a worse prognosis in several cancers, including HNSCC." (PMID 35750900, 2023). "Overexpression of PSMD14 was associated with advanced cancer characteristics and a worse prognosis in various carcinomas." (PMID 35750900, 2023). "Consistent with other cancers, PSMB5, TPR, and PRPF19 were independent prognostic risk factors in BCa, while PSMD14 seemed to be a protective factor, which was different from other types of cancers." (PMID 35898492, 2022). "PSMD14 is known to be associated with several types of cancer and was suggested to be a hub gene in PE." (PMID 36421809, 2022). "Some evidence suggests that PSMD14 can modulate K11‐, K48‐, and K63‐linked polyubiquitin chains in cancer." (PMID 34382324, 2021). "Several other DUBs discussed in this review including DUB3/USP17L2, USP3, and POH1/PSMD14 have been implicated in cancer for their abilities to regulate migration, invasion, and drug resistance." (PMID 32708614, 2020). "The question remains whether PSMD14 may serve as an independent prognostic biomarker in HNSCC or its association with prognosis is a result of upregulation during cancer progression." (PMID 35750900, 2023). "PSMD14 is an essential part of the proteasome and has been linked to prognosis in various cancers." (PMID 35750900, 2023). "Furthermore, high PSMD14 levels were associated with advanced cancer stages in various cancer types." (PMID 35750900, 2023). "Moreover, the interplay between PSMD14 and other tumor-associated genes may further clarify its significance in cancer biology." (PMID 40475775, 2025). "Investigating the role and mechanisms of PSMD14 in these types of cancer could yield transformative insights into their underlying pathogenesis and reveal potential therapeutic targets, thereby creating new possibilities for treatment strategies against these challenging diseases." (PMID 40475775, 2025). "Proteasome 26S subunit non‐ATPase 14 (PSMD14/RPN11/POH1) is a protein‐coding gene that has emerged as a potential prognostic marker for several cancers." (PMID 40066751, 2025). "Contemporary methodologies in cancer research have predominantly concentrated on diverse mechanisms of immune escape; however, the precise relationship between PSMD14 expression and tumor immune infiltration has yet to be adequately examined." (PMID 40475775, 2025). "To gain deeper insights into the impact of PSMD14 expression on cancer patient prognosis, we acquired RNA sequencing and clinical data from TCGA." (PMID 40475775, 2025). "Earlier research has recognized PSMD14 as a deubiquitinase that facilitates tumor progression across multiple cancer forms." (PMID 40475775, 2025). "Accumulating evidence has established the deubiquitinase PSMD14 as a critical promoter of tumor progression across diverse cancers, primarily through a conserved mechanism of stabilizing oncogenic substrates via K63-linked deubiquitination." (PMID 41488674, 2025). "The role of PSMD14 is heterogeneous among different cancer types, with elevated expression levels correlating with diminished OS in patients with LUAD, LIHC, PAAD, and HNSC." (PMID 40475775, 2025).